HSPD1 (heat shock protein family D (Hsp60) member 1)
Diseases named in the same sentence as HSPD1 in open-access papers (continued):
Sharing a sentence is not in itself a finding about the gene and the disease.
tumor (69 papers, 1992 to 2026). "A study published in 2021 demonstrated that loss-of-function mutations in Hspd1 lead to a profound energetic collapse, which directly impairs the ability of cancer cells to proliferate and expand, thereby disrupting tumor progression." (PMID 40427657, 2025). "And former studies indicated that abnormal expression of HSPD1 is associated with tumor cell metastasis and drug resistance 23-25." (PMID 39440061, 2024). "Recently, HSPD1 was associated with carcinogenesis, specifically tumor cell survival and proliferation, in different types of cancer." (PMID 23118872, 2012). "The molecular mechanisms underlying the chemosensitivity of tumor cells expressing high HSPD1 levels, as shown here, remain unclear and require further investigation." (PMID 37508418, 2023). "Furthermore, HSPD1 protein level was inversely correlated with E-cadherin protein level in tumor tissues and co-expression of high HSPD1/low E-cadherin showed a significant association with poor prognosis in BMSCC patients." (PMID 31222140, 2019). "Conversely, HSPD1 may also be associated with tumor suppressors." (PMID 39430254, 2024). "HSPD1 encodes a member of the heat shock protein 60 gene family, could improve the survival rates of tumor cells through the endogenous apoptotic pathway, and promotes tumor cell proliferation via the ROS/AMPK/mTOR pathway." (PMID 33681194, 2021). "Specifically, EV-mediated delivery of si-HSPD1 capitalizes on both the molecular specificity of RNA interference and the tumor-targeting properties of endogenous vesicle systems 25, establishing a novel theoretical framework for precision intervention in PCa." (PMID 41522350, 2026). "siRNA@EVs achieved significant HSPD1 silencing, effectively inhibiting the proliferation and metastasis of PCa cells, and blocking xenografts tumor growth in nude mice with safety." (PMID 41522350, 2026). "Terminal tumor measurements confirmed an 80.6% decrease in sh-HSPD1 xenograft mass (P < 0.01), with gross morphological analysis demonstrating markedly diminished tumor sizes in the knockdown group." (PMID 41522350, 2026). "First, our study showed that naïve T-cells in tumor tissues exhibit increased expression of HSPs, including HSPD1, HSPE1, HSPA1A, HSPA6, and DNAJB1." (PMID 41186645, 2026). "In the analysis of DEGs, we focused on the genes HSPA9 and HSPD1, which influence tumor cell survival by regulating the stability of the mitochondrial membrane and the conformation and thus function of mitochondrial proteins." (PMID 40362672, 2025). "Considering that EMT is critical for tumor invasion, migration, and metastasis, we examined the expression of EMT markers to investigate the mechanisms underlying a potential HSPD1-driven phenotype." (PMID 39430254, 2024). "We performed cell-based assays to measure the apoptosis rate of tumor cells following treatment with different concentrations of the apoptosis inducer ABT737 (the HSPD1 inhibitor), KHS101, or a combination of the two." (PMID 37508418, 2023). "Lower levels of SIGIRR and of TOLLIP, NFRKB, TNFRSF1A, and CD14 and of two distinct MAP kinases were detected in all the cancer cell lines analyzed; on the contrary, IRAK1 and HSPD1 mRNAs were upregulated in all the tumor cells." (PMID 35814450, 2022). "HSPD1 participates in protein folding and regulates apoptosis and immunocompetence, and plays an important role in tumor and infectious disease pathogenicity." (PMID 35805155, 2022).
tumor (continued). "It was previously reported that specific interactions between HSP90 and CYPD, VDAC1 and ANT, and HSPD1 and CypD in mitochondria directly contribute to survival of tumor cells." (PMID 32235444, 2020). "HSPD1 protein level was compared between 128 corresponding tumor adjacent normal (CTAN) tissues and 186 BMSCC tissues on a tissue microarray (TMA) by immunohistochemistry (IHC)." (PMID 31222140, 2019). "In order to further test the prognostic power of these individual mitochondrial biomarkers, we next selected the most promising one, HSPD1, and assessed its ability to predict tumor progression in the whole patient population (N = 726)." (PMID 28978099, 2017). "In this context, this trend was also true for tumor progression, as HSPD1 was a better predictor of time to tumor progression and post-progression survival in non-smokers, with hazard-ratios of 3.64 and 2.89, respectively." (PMID 28978099, 2017). "The presence of HSPD1 in the surface of exosomes was observed in large bowel patients, whose levels were reduced after tumor ablative surgery." (PMID 28468249, 2017). "Several of these involve genes known to be implicated in tumorigenesis or tumor maintenance, like GNAS or HSPD1." (PMID 23537109, 2013). "Simultaneously, the immune-cells around the tumor tissue also showed high immune-intensity for HSPD1 and PGAM-1." (PMID 23118872, 2012). "In addition, we found genes associated with tumor progression were downregulated; among these were heat shock proteins (HSP), such as HSPH1, HSPD1, LYAR and EPHA2." (PMID 38992681, 2024). "Importantly, this study revealed that the expression of HSPD1 and TRAP1, both potential targets for cancer drugs, is linked to sensitivity to certain drug categories in specific tumor types." (PMID 37508418, 2023). "At present, HSPD1 has also been identified to function in tumor progression and modulation of antitumor immune responses; therefore, researchers have advanced the hypothesis that HSPD1 can be used as a target for anticancer therapy." (PMID 35805155, 2022). "In addition, transwell migration and invasion assays showed that circEIF3H overexpression markedly ameliorated the tumor-suppressive effect of HSPD1/RBM8A/G3BP1 silencing." (PMID 35568705, 2022). "Therefore, HSPA9 and HSPD1 can also be further analyzed as the core genes for the study of tumor–endothelium interaction." (PMID 33681194, 2021). "Here, we investigated the tumor-promoting role of HSPD1 and explored if its targeting could interfere with the malignant metabolic mechanisms underlying NSCLC." (PMID 34364401, 2021). "In addition, HSPD1 carries a central role in cancer development, with either pro-survival or pro-apoptotic functions reported in different tumor types." (PMID 34364401, 2021). "HSPD1 was shown to be a specific biomarker for tumor derived circulating cells and LEVs." (PMID 33801459, 2021). "Moreover, heat shock proteins (HSPs) including HSPA8, HSPA9, and HSPD1 in tumor tissues displayed aberrant lysine acetylation modification." (PMID 33093847, 2020). "Our cohort study showed that higher HSPD1 protein level was associated with tumorigenesis and poor prognosis in BMSCC patients with lymph node invasion, suggesting that HSPD1 may be involved in tumor metastasis." (PMID 31222140, 2019). "HSP90B1 and HSPD1 were also expressed at higher levels in cell lines than primary tumours." (PMID 29702669, 2018). "Tumor cell lines, such as hepatocellular carcinoma cell line HepG2 and murine leukemia monocytes cell lines, were described to secrete HSPD1, HSPA1A, and HSP90AA1 in exosomes, which augmented the cytolytic activity of natural killer cells, macrophages and mononuclear cells." (PMID 28468249, 2017).
tumor (continued). "HSPD1 knockdown and pharmacological HSP60 inhibition suppressed proliferation, metastasis, and subcutaneous tumor growth, while overexpression exacerbated oncogenicity." (PMID 41522350, 2026). "Generally, heat shock protein family genes (HSPD1, HSPA1B, HSP90AB1, and HSPH1) enhance tumor growth and invasion through complex intracellular signaling networks." (PMID 37533434, 2023). "Six proteins (LMNA, LCP1, HSPD1, CS, CA1, and ALB) were previously identified as differentially expressed between the tumor center and margin." (PMID 35512017, 2022). "HSPD1 and PSMB4 were observed to show strongly interrelated with neoplasm disease (80%) while GEMIN6 is highly interrelated with nervous system diseases (80%)." (PMID 34918006, 2022). "A previous study reported that miR-942-5p expression is upregulated in OSCC tumor tissues and contributes to OSCC progression, whereas the role of HSPD1 in OSCC progression is still unclear." (PMID 36016581, 2022). "We also analyzed HSPH1, HSPD1, SERPINH1, HSPA4, and HSP90AA1 expression as a function of the HNSC tumor stage." (PMID 32523426, 2020). "In summary, our results indicate that HSPH1, HSPD1, SERPINH1, HSPA4, and HSP90AA1 are significantly upregulated in HNSC patients and their upregulation is negatively correlated with HNSC tumor stage." (PMID 32523426, 2020). "Of this group of genes, HSPD1, HSPE1, CCT3 and CCT5 were overexpressed in Basal, HER2 and Luminal B subtypes (more aggressive BRCA tumours)." (PMID 29954368, 2018). "For instance, HSPD1, a member of the HSP60 gene family, was upregulated in all three tumor cell lines, following OCT4B1 suppression." (PMID 26862520, 2016). "Western blotting was used to quantify the expression of PGAM-1, HSPD1, PDIA3 and SSP411 (which were all upregulated in bile from CC patients) in eight pairs of CC and adjacent non-tumor bile duct tissues." (PMID 23118872, 2012). "PGAM-1, HSPD1, PDIA3 and SSP411 were overexpressed in tumor tissues compared to the matched non-tumor tissues." (PMID 23118872, 2012). "Immunohistochemical analysis was performed to characterize the distribution of PGAM-1, HSPD1, PDIA3 and SSP411 in surgical tumor tissues." (PMID 23118872, 2012). "The elevated expression of HSPs such as HSPD1, HSPE1, HSPA1A, HSPA6, and DNAJB1 suggests that naïve T-cells in tumor tissues may be under a state of stress or heat shock." (PMID 41186645, 2026). "Additionally, the heat shock protein family genes (HSPD1, HSPA1B, and HSP90AB1) facilitate tumor growth and invasion via intricate intracellular signaling networks." (PMID 37533434, 2023). "HSP60 or HSPD1, located on the surface of exosomes secreted by tumor cells but not normal cells, was reported as one of the key players during the progress of cancer." (PMID 35928554, 2022). "In this analysis, HSPD1, a key marker of mitochondrial biogenesis, had the highest predictive value and was also effective in predicting tumor progression in both smokers and non-smokers alike." (PMID 28978099, 2017). "Furthermore, prior research has underscored that E-cadherin downregulation, facilitated through HSPD1 activation, promotes the migration and invasion of OSCC tumour cells into adjacent organs, thus fostering metastatic dissemination and correlating with an unfavourable prognosis." (PMID 38719848, 2024). "Thus, the mitochondrial chaperone, HSPD1, is an effective predictive biomarker of overall survival and tumor progression, in both smokers and non-smokers as well." (PMID 28978099, 2017).
cancer (62 papers, 2004 to 2026). A tumor composed of atypical neoplastic, often pleomorphic cells that invade other tissues. "Recently, exosomal HSPD1 is reported as a potential diagnostic and prognostic biomarker in cancer, especially in colorectal cancer." (PMID 31222140, 2019). "Though antibody responses to F-actin, RUVBL2, and HSPD1 have been reported in other cancers, they are here identified to induce B cell response in PDAC." (PMID 37751306, 2023). "HSPD1 is overexpressed in many cancer types, and its expression has been correlated with the metastatic potential of cancers and the overall survival of cancer patients." (PMID 37508418, 2023). "HSPD1 is constitutively expressed in mitochondria and cytoplasm and plays a key role in chaperoning, thermotolerance, apoptosis, cancer, immunology and embryonic development." (PMID 37587463, 2023). "HSPD1 is a mitochondrial chaperone overexpressed in cancer cells, which is involved in cell proliferation." (PMID 36500393, 2022). "CircEIF3H overexpression significantly promoted TNBC cell proliferation, Edu incorporation and colony formation in TNBC cells, and HSPD1/RBM8A/G3BP1 knockdown attenuated the cancer-promoting effect induced by the circEIF3H overexpression." (PMID 35568705, 2022). "In cancer cells, a higher expression of HSPD1 is needed due to their faster metabolic and proliferation rates, and more intensive protein trafficking between the cytoplasm and mitochondria." (PMID 34575702, 2021). "HSPD1 was a significant cancer-dependent gene in over 70% of the cells, confirming the importance of this gene for NSCLC survival." (PMID 34364401, 2021). "We found, for instance, that 6 cancer-related targets changed their expression levels: HSPD1, PARP1, XRCC5, PRDX2, MTA2 and FASN." (PMID 24801752, 2014). "The diverse array of gene mutations, gene expression patterns, and signaling pathways observed in different cancer types may contribute to the varying roles of HSPD1 in different cancers." (PMID 39430254, 2024). "Furthermore, Pearson's correlation analysis revealed that HSPD1 was positively associated with ATP5A1 in most normal and cancer tissues or cell lines based on the data from GTEx, TCGA, and CCLE databases." (PMID 39430254, 2024). "In the context of cancer, HSPD1 may play a different role, and interventions targeting HSPD1 are expected to destabilize invasive cancer cells and enhance antitumor immunity 34-36." (PMID 39430254, 2024). "In any case, our data clearly indicate the activity of HSPD1 as essential for maintaining NSCLC metabolic fitness and its loss causes a profound energetic breakdown affecting the ability of the cancer cells to divide and expand, making it an attractive therapeutic target." (PMID 34364401, 2021). "HSPD1 is a chaperonin, involved in regulating apoptosis in cancer." (PMID 33261560, 2020). "Moreover, abnormalities in expression and subcellular localization of HSPD1 were also related to neurodegenerative disorders, inflammatory diseases and various cancers." (PMID 31222140, 2019). "With the exception of HSPD1, all targets were downregulated upon combinatorial treatment, suggesting that it can suppress cancer cell survival by affecting the expression levels of these validated cancer-related target genes." (PMID 24801752, 2014). "The diverse functions of HSPD1 in cancer may stem from the activation of various molecular pathways in different types of cancer, highlighting the intricate and diverse nature that defines the complexity of cancer biology." (PMID 39430254, 2024). "Depletion of HSPD1 could block cancer cell viability in an oxidative phosphorylation manner." (PMID 35342421, 2022). "HSPD1 is related to chronic inflammation, which may increase cancer metastasis." (PMID 31222140, 2019).
cancer (continued). "Moreover, HSPD1 expression is associated with recurrence in BMSCC patients, implying that HSPD1 may mediate drug resistance and could be a prognostic factor for cancer therapy." (PMID 31222140, 2019). "While the roles of HSPD1 and KLRG2 play a role in regulating γδ T cell-mediated cytotoxicity in cancer have been described, there is limited information about the involvement of BTNL9 in γδ T cell-mediated killing of cancer cells." (PMID 38090581, 2023). "The expressions of five HSPs members (HSPH1, HSPD1, SERPINH1, HSPA4 and HSP90AA1) in more than 20 types of cancers were detected and compared with expressions in normal tissues using the ONCOMINE database." (PMID 32523426, 2020). "Heat shock protein family D member 1 (HSPD1), as a signaling molecule in the immune system, is dysregulated in various cancers." (PMID 32457797, 2020). "Furthermore, NR2F1 bound HSPD1, which can stabilize ATP5A1 in cancer cells, leading to activation of mTOR signaling." (PMID 40955663, 2025). "Indeed, KHS101-treated NSCLC cells underwent significant cell death, probably due to the formation of irreversible HSPD1 multi-aggregates coagulated by KHS101, which can disrupt the energetic capacity of the cancer cells, as previously shown." (PMID 34364401, 2021). "Additionally, intense expression of PGAM1, HSPD1, and PDIA3 was observed in the cytoplasm of cancer cells in both hilar and intrahepatic CC." (PMID 23118872, 2012). "Moreover, SNO of HSPD1 and PRDX4 were detected in SW 480 cells and human cancer tissue." (PMID 37124724, 2023). "HSPD1 is an ATP-dependent HSP mainly localized in the mitochondria, playing an essential role in guaranteeing the correct folding of the mitochondrial-imported proteins and some data are available on its role as a stemness/metastasis regulator in other cancers." (PMID 34364401, 2021). "For example, HSPD1 correlated with HDPE1 in normal tissues, including breast (Rs = 0.73, FDR < 2.2 × 10−16) and lung (Rs = 0.87, FDR < 2.2 × 10−16), as well as in matched cancer types, including BRCA (Rs = 0.69, FDR < 2.2 × 10−16) and LUAD (Rs = 0.83, FDR < 2.2 × 10−16)." (PMID 33225964, 2020). "Many other proteins thought to be highly abundant in EVs also did not have a pan-cancer expression, including GAPDH, HSPD1, and ENO1." (PMID 36470535, 2023). "In the top 20 upregulated DEGs of lymph node‐derived exhausted CD8+ T cells, CXCL13, CXCR4, CH25H, HSPD1, HSP90AA1, and ATF3 have been confirmed to promote lymph node metastasis in several cancer types." (PMID 35184420, 2022).
infectious disease (5 papers, 2014 to 2025). A disorder directly resulting from the presence and activity of a microbial, viral, or parasitic agent in humans. "HSPD1 has functions in protein folding, regulates apoptosis and immunocompetence, is an important chaperone molecule in mitochondria, and has an important role in the pathogenesis of tumors and infectious diseases." (PMID 35805155, 2022). "Although the interaction between HSPD1 and pathogen proteins has been demonstrated, there is a lack of studies on its known inhibitors or regulators that could represent potential therapeutic agents in infectious diseases." (PMID 35805155, 2022).
neurodegenerative disease (5 papers, 2014 to 2025). A disorder of the central nervous system characterized by gradual and progressive loss of neural tissue and neurologic function. "However, in addition to these canonical roles, Hspd1 participates in the inflammatory response, has a protective role in neurodegenerative diseases, and regulates myelination." (PMID 40299488, 2025).
neurological disorders (5 papers, 2015 to 2022). "Several neurological disorders have been linked to mutations in chaperonin genes and more specifically to the HSPD1 gene." (PMID 32766281, 2020). "Mutations in HSPD1 were associated with diseases of nervous system and inactivation of HSPD1 in mice was embryonically lethal." (PMID 26557144, 2015). "The neurological disorders hereditary spastic paraplegia SPG13 and MitCHAP-60 disease are caused by missense mutations in the HSPD1 gene." (PMID 27774450, 2016).